APC (APC regulator of Wnt signaling pathway)
Diseases named in the same sentence as APC in open-access papers (continued):
Sharing a sentence is not in itself a finding about the gene and the disease.
colorectal cancer (continued). "miR-135a functions as an oncogenic microRNA in colorectal carcinomas by repressing adenomatous polyposis coli (APC)." (PMID 28415713, 2017). "The change of APC gene can not only induce familial adenomatous polyposis, but also is related to the early occurrence of colorectal cancer." (PMID 27065015, 2016). "Although the frequency is lower than that reported in the previous study, the Japanese colorectal cancer samples with RSPO2/3 fusions are similarly positive for the expression of mismatch repair proteins and have the wild-type APC allele." (PMID 27338477, 2016). "Polymorphic variants within TFAP2A have also been shown to interact directly with APC and β-catenin preventing β-catenin from associating with TCF4 and thus blocking transcription of WNT-responsive genes in colorectal cancer cells." (PMID 26697505, 2016). "TNKSi treatment of APC-mutant SW480 colorectal cancer cells can induce axin puncta which act as sites for assembly of β-catenin degradation complexes, however this process is poorly understood." (PMID 26930278, 2016). "In colorectal cancers, miR-135a has been proposed to act as a positive regulator of Wnt signaling by targeting APC, a key molecule of the beta-catenin destruction complex." (PMID 27048518, 2016). "The inhibition or down-regulation of APC expression through APC promoter methylation contributes to the formation of colorectal cancer." (PMID 27478702, 2016). "The main oncoprotein in colorectal cancer is the WNT pathway effector β-catenin, which transportation to the nucleus and overactivation due to genic mutations in the APC, Axin, CKI, and GSK-3β in most cases." (PMID 27613840, 2016). "APC and K-RAS mutations, typically colorectal cancer-associated, were seen in 6 cases (12%), respectively." (PMID 28050231, 2016). "We have further shown that most of these sporadic colorectal carcinomas with LOH for APC do return to copy number neutrality." (PMID 26970738, 2016). "According to these data, a recent paper reported that most of sporadic colorectal carcinomas with LOH for APC return to copy number neutrality with the duplication of the remaining allele." (PMID 27481518, 2016). "Hypermethylation of the APC promoter (18% primary colorectal carcinomas and adenomas) is alternate mechanism." (PMID 27276710, 2016). "We quantified the methylation status of the ITF2 and APC promoter CpG islands in a nested case-case study in two cohorts of colorectal carcinoma from two different populations, comparing cases by MSI status." (PMID 26884349, 2016). "In contrast to sporadic colorectal carcinomas, in which the majority harbors APC, CTNNB1 or KRAS mutations, colorectal carcinomas that arise in the setting of chronic inflammatory diseases have a very low frequency of these mutations." (PMID 26744320, 2016). "The reduction of Wnt/β-catenin signaling, by the tankyrase inhibitors G007-LK and G244-LM, has been also demonstrated in APC mutant colorectal cancer (CRC) cell lines." (PMID 26056602, 2015). "Wnt signaling pathway is aberrantly activated in a variety of cancers, especially in colorectal cancer (CRC), because of mutations in the genes encoding adenomatous polyposis coli (APC), β-catenin and Axin." (PMID 27551464, 2015). "Intestine-specific deletion of FAK almost completely suppressed intestinal adenoma formation in APC-mutant mouse model for colorectal cancer, proving that FAK is required for the oncogenicity of APC mutation in intestinal tumorigenesis." (PMID 26274564, 2015). "The four genes linked to colorectal cancer (NRAS, PIK3CA, MCC, APC) all show lower methylation in the AA/YRI groups." (PMID 25742137, 2015).
colorectal cancer (continued). "Actually, among 599 genome-wide screened large intestine cancer samples, CTNNB1 (encoding β-catenin protein) was mutated in 99 samples, APC was mutated in 427 samples, and both genes were mutated in 78 samples." (PMID 26212640, 2015). "It is certainly without a doubt that a retrotransposition event that occurs within a critical gene, like in the case of APC in colorectal cancer, can be considered as a driving mechanism." (PMID 26448926, 2015). "Truncated forms of adenomatous polyposis coli (APC), a component of the β-catenin destruction complex, are observed in the majority of sporadic colorectal cancer cases." (PMID 25603347, 2015). "The APC gene has been reported as an important tumor suppressor in colorectal cancer, and the aberrant of APC methylation had been reported in numerics for cancers, such as bladder, prostate, breast and lung cancer." (PMID 24661338, 2014). "Multiple mutations are necessary for carcinogenesis, and as APC mutations occur in a large majority of human colorectal cancers, FBXW7 mutations are found mostly in the context of APC mutant alleles." (PMID 23676439, 2014). "WNT-pathway activation is a key factor in the etiology and maintenance of colorectal cancer (CRC), with loss of function mutations in the tumor suppressor APC being the main cause." (PMID 25003333, 2014). "miR-135b has also been reported to induce Wnt signaling pathway by the suppression of APC in colorectal cancers and lung cancer." (PMID 25265336, 2014). "One leading example is colorectal cancer: alterations in Wnt-related genes, mainly APC, have been observed in ~90% of colorectal cancer." (PMID 24474204, 2014). "To address this issue, we performed BN/SDS-PAGE on cytosolic fractions of the SW480 colorectal carcinoma cell line, which expresses APC truncated at position Q1338." (PMID 25392450, 2014). "Tumorigenic retrotransposition in somatic cells was first observed 20 years ago, coincidentally in the APC gene of an individual with colorectal cancer." (PMID 23540693, 2013). "Both MEK/ERK and GSK3 signaling pathways are thought to be affected in early stages of colorectal cancer formation due to frequent mutations in KRAS/BRAF and APC genes respectively." (PMID 23919615, 2013). "In this study, we have modeled regulation by the destruction complex in normal and colorectal cancer cells, which express full-length and truncated APC, respectively." (PMID 24086117, 2013). "Analogously APC is a well characterized tumour suppressor gene, initially identified in colorectal cancer, that plays an integral role in the wnt-signalling pathway and in intercellular adhesion." (PMID 23874531, 2013). "While genetic alterations of Wnt pathway components, such as APC, β-catenin, axin and TCF7L2 are implicated in colorectal cancers, melanoma, gastric and hepatocellular carcinomas, they are rarely associated with breast cancer." (PMID 23516639, 2013). "For example, in colorectal cancer, MAPRE1 binds to the tumor suppressor protein APC which is often mutated in familial and sporadic forms of colorectal cancer." (PMID 23822816, 2013). "Despite the importance of APC in colorectal cancer, little is known about the biophysical properties and/or structure of the APC protein or its cancer-truncated forms." (PMID 24156781, 2013).
colorectal cancer (continued). "Thus, for instance in the case of colorectal cancer we assume a single pathway of initiation involving mutations i and j that appear to be independent losses of the maternal and paternal alleles of the APC gene conjoined to a single pathway of promotion mutations A, B, C, D...." (PMID 24195059, 2013). "In colorectal cancer cells, APC, a tumor suppressor protein, is commonly expressed in truncated form." (PMID 24086117, 2013). "Clones that recognised APC-NT were isotyped and analysed for their ability to immunoprecipitate endogenous APC from MDCK epithelial cells (containing wild-type APC) and SW480 colorectal carcinoma cells (containing mutated, truncated APC)." (PMID 24156781, 2013). "Previous studies have shown that tankyrase inhibitors abrogate Wnt signalling in colorectal cancer cells with mutant APC." (PMID 23144924, 2012). "Genetic mutations of the Wnt/β-catenin signalling intracellular components APC, CTNNB1 (β-catenin encoding gene), and Axin2 are major contributing factors for colorectal cancers." (PMID 23209942, 2012). "As truncated APC seems required for the development of human colorectal cancer, it constitutes a suitable therapeutic target." (PMID 22509309, 2012). "Here, RNA interference has been used to down-regulate truncated APC in several colorectal cancer cell lines expressing truncated APCs of different lengths, thereby performing an analysis covering most of the mutation cluster region (MCR)." (PMID 22509309, 2012). "Recently, the Polyposis in the Rat Colon (Pirc) model is reported as an excellent genetic model of CRC which contains a germline truncation in the adenomatous polyposis coli (APC) tumor suppressor gene, the initiating event in most colorectal cancer." (PMID 23049818, 2012). "Consistent with reported results on APC-mutant colorectal cancer cells, tankyrase inhibitors stabilized Axin1 expression in DU4475 breast cancer cells, that harbor a mutant APC." (PMID 23144924, 2012). "rs367615 is located in an intergenic region within 5q21, where there is one member of the Wnt signaling pathway (APC) known to be important in both familial and non-familial colorectal cancer as well as MCC, perhaps also important in CRC." (PMID 23300701, 2012). "Knockdown of truncated APC reduced the in vitro proliferation of 6 out of 6 human colorectal cancer cell lines and inhibited tumour development by HT29 cells upon transplantation in nude mice." (PMID 22509309, 2012). "We find that APC is hypermethylated more frequently (for example, in 33% of colorectal cancers) but it has multiple TSSs and a promoter that is repressed in normal gastric tissue has been shown to be the site of hypermethylation in gastric cancers." (PMID 23034185, 2012). "We have previously shown that treatment with DNA-alkylating agents enhances the level of APC in colorectal cancer cells." (PMID 21311763, 2011). "Many tumor suppressor genes silencing described in colorectal cancers have been linked to promoter hypermethylation such as p16, MLH1, TSP-1 and APC." (PMID 20423473, 2010). "miR-135 has recently been shown to inhibit expression of the tumor suppressor gene Adenomatous Polyposis Coli (APC) in colorectal cancer." (PMID 20624269, 2010). "Several studies have shown that mutations in the tumor suppressor gene adenomatosis polyposis coli (APC) occur primarily in the basal crypt colonic stem cells, which are presumed tumor initiating colorectal cancer stem cells." (PMID 20641041, 2010). "Both mutational inactivation of the adenomatous polyposis coli (APC) tumor suppressor gene and activation of the KRAS oncogene are implicated in the pathogenesis of colorectal cancer." (PMID 20298593, 2010). "It was shown that mutations in APC and KRAS occur in approximately 80% and 50%, respectively, of sporadic colorectal cancer." (PMID 20298593, 2010).
colorectal cancer (continued). "APC, β-catenin, axin, and GSK-3β mutations can cause increased expression of β-catenin in the cytoplasm and nucleus of colorectal carcinoma, which leads to Wnt pathway activation." (PMID 20346115, 2010). "Furthermore, we hypothesised that if the likelihood of mitotic recombination at APC depended on local sequence variants, there would be clinical implications, because individuals with an inherited tendency to LOH at APC might have an increased risk of colorectal cancer." (PMID 19515250, 2009). "APC gene mutations, as well as KRAS mutations, are recognized as early events in colorectal cancer development." (PMID 19832985, 2009). "We initially screened 49 colorectal cancer cell lines for copy-neutral LOH at APC using the Affymetrix 10 K HuSNP array, alongside array-CGH analysis using a 1 Mb density BAC-based array." (PMID 19515250, 2009). "However, mutations in β-catenin or adenomatous polyposis coli (APC) genes, which appeared in over 90% of colorectal cancers were found only in about 20–30% of HCCs, suggesting that the predominant mechanisms activating Wnt signaling pathway in HCCs could be different from that in other cancers." (PMID 19402906, 2009). "The Adenomatous Polyposis Coli (APC) tumor suppressor gene, maps on chromosome 5q21-22, has been investigated in several types of cancers and in particular colorectal cancers." (PMID 19149902, 2009). "Other studies have reported the interaction between the Rho family GEF Asef and adenomatous polyposis coli (APC), an important component of the Wnt pathway, which leads to increased migration of colorectal cancer cells." (PMID 18826597, 2008). "We therefore set out initially to analyse a protein band (150 kDa), which was detected by a panel of antibodies directed to the N and C termini of APC on Western blots of cell lysates from a number of colorectal cancer cell lines." (PMID 17595655, 2007). "It has been reported that alterations in the APC gene are present in more than 80% of colorectal cancer cases." (PMID 16451736, 2006). "Supporting this, we also observed junctional APC immunostaining in cultures of human colorectal cancer cell line that express truncated forms of APC." (PMID 16423286, 2006). "The pEGFP-APC-N construct used in this study is similar to some of the more extremely truncated APC proteins expressed in colorectal cancer cells." (PMID 16423286, 2006). "Loss-of-function mutations in the adenomatosis polyposis coli (APC) tumour suppressor gene, resulting in deregulation of the WNT-signalling pathway, has been associated with the progression of the majority of colorectal carcinomas." (PMID 16705313, 2006). "In this study, the occurrence of mutations in the APC, CTNNB1 and K-ras genes as well as expression of the hMLH1 protein in tumour tissue of 656 sporadic colorectal cancer cases were investigated." (PMID 16356174, 2005). "Mutations involving components of the Wnt-signalling cascade, specifically in APC or β-catenin, are essential for the initiation of colorectal cancer." (PMID 14710233, 2004). "Inherited mutations in APC lead to the condition known as familial adenomatous polyposis (FAP), which predisposes the affected individuals to colorectal cancer." (PMID 12610503, 2003). "As a control of APC expression, a normal colon sample and a colorectal carcinoma (CRC; Duke A) from the same patient was included." (PMID 14520463, 2003).
colorectal cancer (continued). "Thirty-four primary, untreated sporadic breast cancers were examined for loss of heterozygosity (LOH) at tumour suppressor loci involved in colorectal cancer: APC/MCC at 5q21 and DCC at 18q21." (PMID 8318422, 1993). "As this suggests the model was capturing signals related to colorectal cancer rather than the effects of APC mutations, the second-best mode of analysis was selected which utilized a balanced set of colorectal cancers for analysis." (PMID 40775769, 2025). "In this context, we present a case of a patient exhibiting polyposis coli, colorectal cancer, atypical leukemia and cerebral tumour who carries pathogenic variants in the CHEK2 and JAK2 genes and one variant of uncertain significance (VUS) in APC." (PMID 40177144, 2025). "The majority of colorectal cancer CRCs exhibit genetic changes in the WNT pathway, such as APC mutations, activating mutations in CTNNB1 (β-catenin), etc., which could encourage the initial growth of the tumor." (PMID 40240755, 2025). "Given that mutations in APC, KRAS, and BRAF are among the most frequently occurring genetic alterations in colorectal cancer, our findings suggest that the Prkci–c-Myc axis may represent a generalizable and mutation-independent oncogenic mechanism in CRC." (PMID 41188443, 2025). "Furthermore, the mouse model used in this study was tailored to APC and KRAS mutations in colorectal cancer, limiting the applicability of the findings to other genetic alterations or tumor types." (PMID 41285904, 2025). "The APC gene plays a key role in the adenoma-carcinoma sequence hypothesis, which explains the progression of colorectal cancer." (PMID 40740242, 2025). "In colorectal cancer, the same database reports 40% of KRAS and 65% of APC variants." (PMID 40916582, 2025). "And SLC7A7 is enriched during the EMT process and may facilitate colorectal cancer metastases through the SLC7A7/APC/WNT/β‐catenin signaling pathway." (PMID 41176774, 2025). "Some well-established nLTR-derived examples include de novo Alu insertions into BRCA1 and BRCA2, which predispose carriers to hereditary breast and ovarian cancers, and germline L1 insertions into the APC TSG, which underlie familial adenomatous polyposis and increase colorectal cancer risk." (PMID 40950107, 2025). "The APC p.Ile1307Lys variant is considered actionable in the Ashkenazi population due to its established association with colorectal cancer risk, yet current evidence does not support its inclusion in actionable screening panels for other populations." (PMID 40970488, 2025). "The APC variant (rs41115, COSM3760869) exhibited stage-dependent prevalence (92% overall; 87% in advanced vs. 100% in early-stage HCC) and has been reported in colorectal cancer." (PMID 41567639, 2025). "In colorectal cancers, RNF43 mutation contexts exhibit an ANT relationship with APC truncating mutations, particularly associated with MSI status, i.e., RNF43 mutations are prevalent in MSI-H tumors but APC mutations are relatively enriched in MSS cases." (PMID 39160568, 2024). "In colorectal cancer, APC exhibits various hotspots, including APC−213 and APC−876." (PMID 38473427, 2024). "Thus, APC alterations were highly associated with colorectal cancer; KRAS alterations and normal APC were highly associated with pancreatic cancer; and CDKN2A alterations and normal APC and KRAS were highly associated with biliary tract cancer." (PMID 38672586, 2024).